SAMHD1 (SAM and HD domain containing deoxynucleoside triphosphate triphosphohydrolase 1)
Diseases named in the same sentence as SAMHD1 in open-access papers (continued):
Sharing a sentence is not in itself a finding about the gene and the disease.
HIV-1 infection (continued). "The SAMHD1 mutant proteins were then tested for inhibition of HIV-1 infection using the two-colour restriction assay." (PMID 26431200, 2015). "This activation process correlates with enhanced cell permissivity to HIV-1 infection and with SAMHD1 phosphorylation." (PMID 26606981, 2015). "T592 phosphorylation was shown to abolish the restrictive capacity of SAMHD1 and to make cells permissive to HIV-1 infection." (PMID 26121641, 2015). "In terminally differentiated macrophages and dendritic cells, or resting CD4+ T-cells with arrested cell cycle (G0/G1), dNTP levels are significantly decreased by SAMHD1, and therefore HIV-1 infection is restricted." (PMID 26416562, 2015). "SAMHD1 acts as the host restriction factor that inhibits human immunodeficiency virus type 1 (HIV-1) infection by reducing intracellular dNTP levels." (PMID 26416562, 2015). "The SAMHD1 triphosphohydrolase inhibits HIV-1 infection of myeloid and resting T cells by depleting dNTPs." (PMID 25856754, 2015). "This sensitivity has an important impact on HIV-1 tropism, with evidence that SAMHD1 prevents HIV-1 infection of dendritic cells and resting T cells." (PMID 25011104, 2014). "The discovery of SAMHD1 as a restriction factor goes back to the observation that HIV-1 infection is inefficient in quiescent myeloid cells such as dendritic cells." (PMID 24854580, 2014). "SAMHD1 was reported to suppress HIV-1 infection of cells of myeloid lineage, including monocyte-derived macrophages." (PMID 24599229, 2014). "SAMHD1 silencing phenocopied the effect of Vpx-containing VLPs in that it rescued HIV-1 infection of both differentiated THP-1 monocytic cells and MDDCs." (PMID 24782834, 2014). "Degradation of SAMHD1 via experimental Vpx delivery results in dendritic cell activation during HIV-1 infection and allows these cells to prime a T cell response." (PMID 24854580, 2014). "Consistent with observations made using cell lines, our data in MDM demonstrate that cytoplasmic SAMHD1 is still able to inhibit HIV-1 infection and is less sensitive to VpxMAC induced degradation." (PMID 24712655, 2014). "In the presence of SAMHD1, the amount of reverse transcription products made in dendritic cells during HIV-1 infection is reduced due to low dNTP concentrations and possibly other mechanisms." (PMID 24854580, 2014). "To confirm that the observed enhancing effect of VSV-G-pseudotyped HIV-2 particles on HIV-1 infection was due to degradation of SAMHD1 in monocytes and macrophages, we used siRNAs targeting SAMHD1 to reduce levels of SAMHD1 expression." (PMID 24599229, 2014). "It has been reported that DCAF1/VprBP is recruited by HIV-2/SIVsmm/mac Vpx to hijack the CUL4–DDB1 E3 ubiquitin ligase complex for degradation of host-restrictive factor SAMHD1, facilitating HIV-1 infection in myeloid cells." (PMID 24932481, 2014). "This study suggests that cytokine-induced upregulation of SAMHD1 in macrophages or DCs can further protect these important antigen-presenting cells from direct HIV-1 infection in vivo." (PMID 24523981, 2013). "The functions of Vpx-mediated SAMHD1 degradation and enhancement of HIV-1 infection of myeloid cells are observed in most HIV-2-infected individuals including all seven patients who developed AIDS." (PMID 24523981, 2013). "Accordingly, we show that the C terminus is required for the full ability of SAMHD1 to deplete dNTP pools and to inhibit HIV-1 infection in U937 monocytes." (PMID 23426366, 2013). "Together, this evidence supports the model in which SAMHD1 inhibits HIV-1 infection indirectly, by depleting dNTP pools to levels below the threshold required for viral reverse transcriptase to function efficiently." (PMID 23426366, 2013). "The authors further demonstrated that the inhibition of HIV-1 infection in monocyte-derived macrophages by Vpx-mediated proteasome degradation of SAMHD1 through the cellular E3 ubiquitin ligase complex." (PMID 24523981, 2013).
HIV-1 infection (continued). "Chemical cross-linking studies revealed SAMHD1 tetramers in human monocytic cells, in which it strongly restricts HIV-1 infection." (PMID 23426366, 2013). "Such evidence highlights the role of alternative regulatory pathways to control of HIV-1 infection, such as miRNA or post-transcriptional modifications; and the potential relationship between alterations in SAMHD1 activity and disease progression." (PMID 24167505, 2013). "It is conceivable that SAMHD1-restriced HIV-1 infection in DCs would limit viral spreading from DCs to CD4+ T-cells, although the experimental evidence is lacking." (PMID 24523981, 2013). "More recent studies also showed evidence for IFN alpha-induced but SAMHD1-independent cellular inhibitors of early HIV-1 infection in several cell lines." (PMID 24523981, 2013). "Although it is possible that low residual amounts of SAMHD1 were able to exert an effect, the data collectively suggest that SAMHD1 is, if at all, only a minor contributor to the IFNα-induced early block to HIV-1 infection in these cells." (PMID 23442224, 2013). "In this report, we used several primary and immortalized cell types to examine the relationship between SAMHD1 expression and function, and the inhibition of HIV-1 infection by IFNα." (PMID 23442224, 2013). "Several sequences located outside the catalytic domain appeared to positively or negatively modulate the ability of SAMHD1 to restrict HIV-1 infection." (PMID 23426366, 2013). "Here, we report that SAMHD1 significantly blocked single-cycle and replication-competent HIV-1 infection of DCs by decreasing the intracellular dNTP pool and thereby limiting the accumulation of HIV-1 late reverse transcription products." (PMID 23231760, 2012). "Two recent studies revealed that SAMHD1 restricts HIV-1 infection in resting CD4+ T-cells, providing new insights into the mechanisms of HIV-1 restriction in non-cycling cells." (PMID 23092163, 2012). "The HIV-1 restriction factor SAMHD1 inhibits HIV-1 infection in human myeloid cells and can be counteracted by the Vpx protein of HIV-2 and the SIVsm lineage." (PMID 22574228, 2012). "Acting as a deoxynucleoside triphosphate (dNTP) triphosphohydrolase, SAMHD1 hydrolyzes dNTPs and restricts HIV-1 infection in macrophages and resting CD4+ T-cells by decreasing the intracellular dNTP pool." (PMID 23231760, 2012). "The increase in HIV-1 infection of myeloid cells in the presence of Vpx-mediated SAMHD1 degradation has been attributed to increased production of late HIV-1 reverse transcription products, which constitute full-length viral cDNA." (PMID 23231760, 2012). "Given the striking ability of SIV Vpx to stimulate HIV-1 infection of myeloid cells by inhibiting SAMHD1, it is puzzling as to why HIV-1 appears to lack an equivalent activity against SAMHD1." (PMID 23344558, 2012). "We confirmed that Vpx-mediated degradation of SAMHD1 enhanced both single-cycle and replication-competent HIV-1 infection in DCs." (PMID 23231760, 2012). "We show that Vpx-mediated degradation of SAMHD1 in DCs significantly enhances HIV-1 infection and accumulation of late reverse transcription products, and increases the intracellular dNTP pool." (PMID 23231760, 2012). "In the current study, we examined the role of SAMHD1 in restricting HIV-1 infection of DCs and compared SAMHD1 expression levels following treatment with IFNs." (PMID 23231760, 2012). "Our results indicate that SAMHD1 functions as an important restriction factor to counteract HIV-1 infection in DCs." (PMID 23231760, 2012). "Recently, two independent groups identified sterile alpha motif (SAM) and histidine/aspartic acid (HD) domain containing protein 1 (SAMHD1) as a novel restriction factor that inhibits HIV-1 infection of myeloid cells." (PMID 23336082, 2012).
HIV-1 infection (continued). "Although SAMHD1 imposes an important block to HIV-1 infection, disruption of this block cannot restore HIV-1 replication in resting CD4+ T cells, indicating that there are additional blocks in these cells." (PMID 23254112, 2012). "We confirm in this study that Vpx interacts with SAMHD1 leading to ubiquitin-mediated degradation of SAMHD1, and renders CD14 positive monocytes susceptible to HIV-1 infection." (PMID 22174685, 2011). "Taken together, we propose that SAMHD1 protects primary CD14+ monocytes from HIV-1 infection confirming SAMHD1 as a potent lentiviral restriction factor." (PMID 22174685, 2011). "Two recent publications identified Sterile Alpha Motif (SAM) Domain and HD domain-containing protein 1 (SAMHD1) as the Vpx-sensitive restriction factor that inhibits HIV-1 infection of macrophages and dendritic cells." (PMID 22174685, 2011). "Understanding cell-type specific barriers to HIV-1 infection such as mediated by SAMHD1 will be important to develop innovative therapies and vaccines." (PMID 22174685, 2011). "Two recent studies discovered the cellular protein SAMHD1 to be this restriction factor, demonstrating that Vpx induces proteasomal degradation of SAMHD1 and enhances HIV-1 infection in myeloid-lineage cells." (PMID 21740548, 2011). "We conclude that monocytes express SAMHD1 as an interferon-inducible factor that is degraded upon Vpx-supported HIV-1 infection confirming the results in dendritic cells and macrophages." (PMID 22174685, 2011). "Furthermore, this observation aligns with previous studies demonstrating that DCs restrict productive HIV-1 infection through multiple mechanisms, including SAMHD1-mediated dNTP depletion, cGAS sensing, and other intrinsic antiviral defenses." (PMID 41596493, 2026). "Therefore, SAMHD1 promotes apoptosis induced by replication-competent HIV-1 infection in dividing THP-1 cells." (PMID 40434097, 2025). "HIV-1 replication is required for SAMHD1-enhanced apoptosis to HIV-1 infection." (PMID 40434097, 2025). "Furthermore, SAMHD1-enhanced apoptosis was associated with increased BIK expression, and BIK contributed to SAMHD1-enhanced apoptosis during HIV-1 infection." (PMID 40434097, 2025). "Moreover, a small-molecule inhibitor (SMI) of SAMHD1 dNTPase efficiently promoted HIV-1 infection and RT to the same extent as SIVmac239 Vpx treatment, while the Vpx treatment did not further promote HIV replication in the presence of SMI." (PMID 40277359, 2025). "Interestingly, HIV-1 infection promoted SAMHD1 expression in U937 SAMHD1 cells, which was reverted by NVP treatment." (PMID 40434097, 2025). "This suggests that, in naïve CD4+ T cells, SAMHD1 may function independently of MxB to counteract HIV-1 infection." (PMID 40277359, 2025). "To investigate whether SAMHD1 enhances apoptosis induced by HIV-1 infection through the mitochondrial apoptotic pathway, we measured Δψm of cells during HIV-1 infection." (PMID 40434097, 2025). "In a selective, shRNA-mediated knockdown screen in primary monocyte-derived dendritic cells (MDDCs) infected with HIV in the presence of SAMHD1-disactivating Vpx containing virus-like particles, three proteins hampering HIV-1 infection were identified: FNBP1L, ARHGAP24, and ATP6V1B1." (PMID 40029073, 2025). "Thus, SAMHD1 reconstitution in THP-1 SAMHD1 KO cells enhances apoptosis induced by single-cycle HIV-1 infection." (PMID 40434097, 2025). "Whether ARD1-enhanced K405 acetylation promotes dNTPase-dependent SAMHD1 restriction on HIV-1 infection can be further confirmed and investigated in the future." (PMID 40277359, 2025). "Indeed, SAMHD1 reconstitution suppressed HIV-1 infection in PMA-differentiated U937 cells as indicated by a decrease in expression level of Gag and CA." (PMID 40434097, 2025). "The reduced BIK protein level in SAMHD1 KO cells might have failed the required threshold for BIK protein to trigger apoptosis for HIV-1 infection in THP-1 cells." (PMID 40434097, 2025).
HIV-1 infection (continued). "In terms of antiviral functions, it was observed that destroying the dNTPase active sites of SAMHD1 by mutating H206 and D207 abolished SAMHD1 restriction on HIV-1 infection in non-dividing myeloid cells." (PMID 40277359, 2025). "We investigated the effects of acetylation on the ability of SAMHD1 to block HIV-1 infection in non-cycling U937 cells by first making SAMHD1 variants that cannot be acetylated." (PMID 39162568, 2024). "The ability of SAMHD1 to block HIV-1 infection is limited to non-cycling cells, a hallmark of this function, and this ability is prevented by the phosphorylation of T592." (PMID 39162568, 2024). "This SAMHD1 mutant lost the ability to inhibit HIV-1 infection in differentiated U937 cells." (PMID 38888311, 2024). "In non-cycling cells, SAMHD1 is preferentially acetylated at K580, suggesting that this post-translational modification may contribute to the ability of SAMHD1 to block HIV-1 infection." (PMID 39162568, 2024). "SAMHD1 inhibited HIV-1 infection by 80% in the control U937 cells (compare bars 1 and 2)." (PMID 38888311, 2024). "Although phosphorylation of threonine 592 (T592) in SAMHD1 is recognized as the primary regulator of the ability to prevent HIV-1 infection, the contributions of SAMHD1 acetylation to this ability remain unknown." (PMID 39162568, 2024). "Indeed, IL-12 signaling has been previously linked to the regulation of cell polarization through the regulation of SAMHD1 in HIV-1 infection, showing also a direct correlation between SAMHD1 expression and IL-12/IL-18 presence." (PMID 37667113, 2024). "The natural inhibitor of HIV-1, sterile alpha motif (SAM) domain- and histidine–aspartic acid (HD) domain-containing protein 1 (SAMHD1), plays a pivotal role in preventing HIV-1 infection of macrophages and dendritic cells, which are vital components of the immune system." (PMID 39162568, 2024). "Subsequent work found SAMHD1 also restricts HIV-1 infection in resting CD4+ T-cells." (PMID 39205287, 2024). "Our investigations revealed the acetylation of K580 in endogenously expressed SAMHD1 and showed that preventing acetylation via K580 point mutations abolished the ability of SAMHD1 to block HIV-1 infection without affecting other known properties of SAMHD1." (PMID 39162568, 2024). "Sterile-motif/histidine-aspartate domain-containing protein 1 (SAMHD1), a host restriction factor possessing dNTP triphosphohydrolase activity, has been reported to restrict HIV-1 infection in monocyte-derived macrophages (MDMs) by reducing the intracellular dNTP pool." (PMID 37298575, 2023). "In addition, SAMHD1 suppresses the innate immune response to viral infections, including HIV-1 infection, and inflammatory stimuli by inhibiting NF-κB activation and type I IFN induction." (PMID 37298575, 2023). "This cell system is an interesting physiological model for HIV-1 infection in macrophage-like cells, as we were able to show that SAMHD1 is completely dephosphorylated at residue T592 in transdifferentiated BLaER1 cells and serves as a major restriction factor for HIV-1." (PMID 37800914, 2023). "Furthermore, we investigated the role of SAMHD1 inhibition of IRF7-mediated IFN-I induction during HIV-1 infection." (PMID 37328105, 2023). "Given that HIV-1 infection results in mucosal barrier dysfunction and the translocation of microbes and microbial products (including LPS), we hypothesize that SAMHD1 may contribute to these defects in IgA SHM." (PMID 35938870, 2022). "In addition, it is capable of increasing the availability of dNTPs and therefore favoring HIV-1 infection thanks to the blocking SAMHD1, a restriction factor that allows DCs to escape productive HIV-1 infection." (PMID 35058917, 2021). "Furthermore, we demonstrate that SAMHD1 suppression of NF-kB activation during HIV-1 infection involves the TRAF6-TAK1 axis." (PMID 33177202, 2021). "As previously reported, the T592A mutant hampered HIV-1 infection as efficiently as WT SAMHD1." (PMID 34321470, 2021).
HIV-1 infection (continued). "Vpx relieves inhibition of HIV-1 infection of myeloid cells mediated by the SAMHD1 protein." (PMID 34630422, 2021). "Therefore, we next evaluated the regulatory impact of SAMHD1 on TAK1 activation during HIV-1 infection." (PMID 33177202, 2021). "However, our group previously illustrated that bypassing SAMHD1 by phosphorylation through HIV-C in iDCs significantly enhanced productive HIV-1 infection and subsequent antiviral humoral and cellular immunity in vitro." (PMID 32922405, 2020). "Furthermore, we show by SAMHD1 knockdown that the TLR4-activated pathway potently blocks HIV-1 infection in macrophages specifically via SAMHD1." (PMID 32209460, 2020). "HDACi also inhibited HIV-1 infection in macrophages in a SAMHD1-dependent manner." (PMID 32751972, 2020). "Additionally, in parallel experiments measuring the permissiveness of AS1842856 treated cells to HIV-1 infection, we also observed a relationship between SAMHD1 phosphorylation levels and GAG expression." (PMID 31042779, 2019). "For examples, SAM domain- and HD domain-containing protein 1 (SAMHD1) inhibits HIV-1 infection of dendritic cells and T cells by reducing the cellular deoxynucleoside triphosphate (dNTP) concentration to a level at which the viral reverse transcriptase cannot function." (PMID 31450557, 2019). "In secondary lymphoid organs, Tfh cells from infected patients lacked the expression of SAMHD1, which was accompanied by a higher susceptibility to HIV-1 infection in vitro." (PMID 31220191, 2019). "In conclusion, SAMHD1 is a double-edged sword during HIV-1 infection since on one hand, it contributes to HIV-1 restriction, but on the other hand it might compete with the activation of innate and adaptive immune responses." (PMID 31426525, 2019). "Furthermore, SAMHD1 prevents virus replication and thus the generation of reverse transcription products in DCs which decreases their ability to sense HIV-1 infection and to trigger their activation." (PMID 31426525, 2019). "Since SAMHD1 dephosphorylation at T592 by PP2A-B55α holoenzymes reduces HIV-1 infection efficiency, we tested whether HIV accessory proteins actively alter B55α subunit expression." (PMID 29884836, 2018). "SAMHD1 is a critical restriction factor regulating HIV-1 infection of macrophages." (PMID 29764952, 2018). "As a consequence, we were interested whether even in cycling cells dephosphorylated SAMHD1 would be able to reduce HIV-1 infection." (PMID 29884836, 2018). "Indirect evidence that SAMHD1 is functional even in cycling cells with high dNTP pools comes also from two recent reports that tested the sensitivity to some nucleoside analogs in cancer cells and in cells permissive to HIV-1 infection." (PMID 30039733, 2018). "NCS treatment was associated with a decrease in phosphorylated SAMHD1 and ISG expression, either or both of which could have been responsible for the block to HIV-1 infection." (PMID 29515139, 2018). "Additionally, SAMHD1 inhibits HIV-1 infection of DCs, which delays the sensing of HIV-1 infection and the onset of immune responses, consequently leaving the virus a longer time window to establish local infection, the foot hold for later systemic infection." (PMID 29342871, 2018). "Also note that topoisomerase inhibitors and chemotherapeutic drugs, albeit indirectly, trigger SAMHD1 antiviral functions by inducing DNA damage, therefore suppressing HIV-1 infection and limiting the size of the viral reservoir." (PMID 30574147, 2018). "Furthermore, we demonstrate that SAMHD1 activity can be manipulated pharmacologically to render macrophages refractory to HIV-1 infection." (PMID 29764952, 2018). "We sought to determine whether IFNs from various families could differentially modulate SAMHD1 protein levels or activity and whether these changes would in turn affect HIV-1 infection in macrophages." (PMID 29764952, 2018).